VRK1 (VRK serine/threonine kinase 1)
Diseases named in the same sentence as VRK1 in open-access papers (continued):
Sharing a sentence is not in itself a finding about the gene and the disease.
glioblastoma (10 papers, 2013 to 2026). The most malignant astrocytic tumor (WHO grade IV). "VRK1 depletion caused a similar effect on the 8-oxoG levels in LN229 glioblastoma cells exposed to hydrogen peroxide, but the oxidative damage response was slower and detected at a later time." (PMID 38732093, 2024). "In Glioblastoma, knocking down VRK1 leads to decreased BAF activity, which in turn causes nuclear lobulation, blebbing, and micronucleation, resulting in G2-M arrest and DNA damage occurring as a result of these cellular alterations." (PMID 38157278, 2023). "Recently VRK1 was shown as a synthetic lethal target in VRK2-deficient glioblastoma and more globally in VRK2-promoter methylated cancers of the central nervous system, including DMG." (PMID 37886173, 2023). "VRK1 was also shown to regulate G1/S transition in fibroblasts but was recently associated with G2/M arrest in glioblastoma, suggesting a cell-dependent impact on cell cycle." (PMID 37886173, 2023). "Depletion of the VRK1 chromatin kinase in glioblastoma cells enhances the DNA damage caused by temozolomide and olaparib treatments." (PMID 34195200, 2021). "High levels of VRK1 have been associated with resistance to treatment in glioblastomas." (PMID 34195200, 2021). "Vaccinia-related kinase 1 (VRK1) is a promising therapeutic target in gliomas and glioblastomas where VRK2 is silenced by promoter methylation, rendering VRK1 essential for accurate nuclear envelope reassembly following mitosis." (PMID 41796804, 2026). "Targeting VRK1 in glioblastoma cells, neuroblastomas, and pediatric gliomas, in which VRK2 has been eliminated or silenced by VRK2-promoter methylation cells, is a potential synthetic lethality strategy in these tumors." (PMID 38753965, 2024). "Depletion of VRK1 sensitizes glioblastoma (GBM) cells to PARP inhibitors, such as olaparib, by facilitating DNA damage in tumor cells and reducing their viability." (PMID 38753965, 2024). "In GBM, VRK1 depletion impaired the formation of H4K20me2 that is required for the recruitment of 53BP1 to damaged DNA sites in glioblastoma cells treated with temozolomide and olaparib." (PMID 38753965, 2024). "Targeting VRK1 has been shown to be a suitable target in glioblastomas in which the VRK2 gene is silenced." (PMID 37179361, 2023). "Depletion of VRK1 in combination with TMZ and olaparib in glioblastoma cells causes an increase in DNA damage at lower doses, which results in tumor cell death." (PMID 34195200, 2021). "The combination of these drugs in VRK1 depleted cells resulted in an increase of glioblastoma cell death detected by annexin V and the processing of PARP-1 and caspase-3." (PMID 34195200, 2021). "We have shown that VRK1 depletion sensitizes tumor cells to two types of pharmacological treatments, temozolomide, a drug used in glioblastoma, and olaparib, an inhibitor of PARP-1 that is in use for the treatment of tumors with BRCA1 mutations." (PMID 34195200, 2021). "In this report, we have studied the effect that VRK1 depletion has in glioblastoma cells, based on the observation that VRK1 is a chromatin kinase which regulates several steps in the DDR and impairs the NHEJ pathway." (PMID 34195200, 2021). "The effect of VRK1 depletion on H3K9 has also been detected in human glioblastoma cell lines." (PMID 37179361, 2023). "Thus, we propose the VRK1 kinase as a good candidate target for novel therapeutic strategies based on synthetic lethality in glioblastomas." (PMID 34195200, 2021). "Alternatively, the interference with the chromatin kinase VRK1, could be a novel alternative strategy of synthetic lethality in glioblastomas." (PMID 34195200, 2021). "Oxidative stress induced an increase in the H4K16ac levels that were impaired by the VRK1 depletion in A549 cells and in LN229 glioblastoma." (PMID 38732093, 2024).
glioblastoma (continued). "The effects of oxidative stress were also determined in cells in which VRK1 was depleted using two different siRNAs (siVRK1-02 and siVRK1-03) for 72 h in A549 lung adenocarcinoma and LN229 glioblastoma cells." (PMID 38732093, 2024). "For this aim the expression and subcellular localization of VRK1 and VRK2 proteins was determined in three glioblastoma cell lines, A172, LN18 and LN229 by immunofluorescence, and the pattern detected was similar to that observed in astrocytoma biopsies." (PMID 24079673, 2013). "Depletion of VRK1, an enzyme that regulates chromatin dynamic reorganization and facilitates resistance to DNA damage, was performed in glioblastoma cells treated with temozolomide, an alkylating agent used for GBM treatment; and olaparib, an inhibitor of PARP-1, used as sensitizer." (PMID 34195200, 2021).
glioma (9 papers, 2016 to 2026). A benign or malignant brain and spinal cord tumor that arises from glial cells (astrocytes, oligodendrocytes, ependymal cells). "The levels of VRK1 (Vaccinia-related kinase 1) also show a clinical significance in human gliomas, and high levels of VRK1 are indeed associated with a poor prognosis." (PMID 40507925, 2025). "At a clinical level, VRK1 overexpression has been associated with poor prognosis in many solid tumors including high-grade glioma." (PMID 37886173, 2023). "Clinically, VRK1 expression has been associated with high grade and poor prognosis in patients with glioma, whereas VRK2 expression is correlated with improved survival in high-grade astrocytoma." (PMID 36040810, 2022). "High levels of VRK1 has been associated as a bad prognostic indicator to several tumors such as breast, gliomas, colon, lung, and hepatocarcinomas among others." (PMID 31101118, 2019). "Using this data set, we found that VRK1 was a strong genetic dependency in the adult glioma (P = 2 × 10–12; Student’s t test; n = 61) and pediatric NB (P = 3 × 10–8; Student’s t test; n = 20) lineages." (PMID 36040810, 2022). "VRK1 is a selective dependency in adult and pediatric glioma and NB." (PMID 36040810, 2022). "Taken together, we observed in 3 independent models and cancer lineages that VRK1 depletion leads to tumor repression in vivo, suggesting that VRK1 is a potential therapeutic target in VRK2 promoter–methylated adult and pediatric gliomas and neuroblastomas." (PMID 36040810, 2022). "Together, these studies identify VRK1 as a synthetic lethal target in VRK2 promoter–methylated adult and pediatric gliomas and neuroblastomas." (PMID 36040810, 2022). "In addition, the DepMap includes a pediatric glioma model (KNS42), which also demonstrated strong VRK1 dependency." (PMID 36040810, 2022).
amyotrophic lateral sclerosis (7 papers, 2018 to 2025). Amyotrophic lateral sclerosis (ALS) is a neurodegenerative disease characterized by progressive muscular paralysis reflecting degeneration of motor neurons in the primary motor cortex, corticospinal tracts, brainstem and spinal cord. "VRK1 plays roles in spermatogenesis in mice and its mutations are linked to developments of neurodegenerative diseases such as amyotrophic lateral sclerosis (ALS)." (PMID 32266931, 2020).
esophageal squamous cell carcinoma (7 papers, 2017 to 2025). Esophageal squamous cell carcinoma (ESCC) is a type of esophageal carcinoma (EC) that can affect any part of the esophagus, but is usually located in the upper or middle third. "VRK1 promotes cell proliferation and migration in gastric cancer cells, esophageal squamous cell carcinoma, bladder cancer, and we derived the same results in LUSC." (PMID 37547297, 2023). "These indicate a possible cancer type-dependent action of VRK1, as higher apoptotic activity was detected in esophageal squamous cell carcinoma cells after VRK1 downregulation." (PMID 33233777, 2020). "Luteolin inhibits vaccinia-related kinase 1 (VRK1) to enhance the efficacy of cisplatin in esophageal squamous cell carcinoma." (PMID 31245292, 2019). "ROC curve analysis identified VRK1 and BANF1 as potential therapeutic targets for esophageal squamous cell carcinoma." (PMID 40384864, 2025). "VRK1 downregulation reduces the expression of BAF and inhibited the proliferation and migration of esophageal squamous cell carcinoma (ESCC)." (PMID 38753965, 2024). "Studies have also pointed out that VRK1 promotes cisplatin resistance by upregulating c-MYC through c-Jun activation and serves as a therapeutic target for esophageal squamous cell carcinoma." (PMID 35559251, 2022).
hepatocellular carcinoma (7 papers, 2015 to 2025). A malignant tumor that arises from hepatocytes. "To decipher the regulatory mechanism by which VRK1 promotes proliferation and migration in hepatocellular carcinoma, we performed immunoprecipitation followed by mass spectrometry (IP-MS) to distinguish the potential interacting proteins of VRK1." (PMID 40234378, 2025). "Recently, it was reported that VRK1 responds to glucose leads to regulate gluconeogenesis through phosphorylation of pregnane X receptor (PXR) in human hepatoma-derived HepG2 cells." (PMID 32266931, 2020). "Taken together, VRK1 enhances the proliferation and migration of hepatocellular carcinoma cells." (PMID 40234378, 2025). "These authors have also shown that VRK1 plays a crucial role in G1/S transition and that its depletion induces a G1 arrest by downregulating cyclin D1 and phospho-RB, and upregulating P21 and P27 in hepatocellular carcinoma." (PMID 37886173, 2023). "For example, the consumption of VRK1 can delay cell cycle progression and reduce the proliferation of liver cancer cells, that is, the high expression of VRK1 contributes to the cell proliferation and survival of hepatocellular carcinoma." (PMID 35559251, 2022). "We identified the specific role of vaccinia-related kinase 1 (VRK1) in the progression of hepatocellular carcinoma (HCC) and evaluated its therapeutic and prognostic potential." (PMID 26375549, 2015). "Previously, glucose was suggested to regulate VRK1, in which low glucose activates VRK1 to phosphorylate PXR at Ser350, inducing transcription of the PEPCK1 and gluconeogenesis in human hepatoma-derived HepG2 cells." (PMID 32266931, 2020). "In addition, VRK1 and HNRNP A1 are frequently overexpressed in several human cancers, including hepatocellular carcinoma (HCC) and the overexpression of VRK1 and HNRNP A1 is correlated with a poor prognosis for HCC patients." (PMID 34071140, 2021).
head and neck squamous cell carcinoma (6 papers, 2008 to 2023). A squamous cell carcinoma that arises from any of the following anatomic sites: lip and oral cavity, nasal cavity, paranasal sinuses, pharynx, larynx, and salivary glands. "Moreover, in human cancer, VRK1 has been associated to the proliferation phenotype and is co-expressed with Ki67 in head and neck squamous cell carcinoma." (PMID 24731990, 2014). "In head and neck squamous cell carcinoma, the VRK1 protein is positively correlated with several proliferation-related proteins including CDK2, CDK6, Cdc2, Cyclin B1/A, topoisomerase II (TOP2), survivin, and Ki67, suggesting that VRK1 can regulate the cell cycle." (PMID 36770809, 2023). "The correlation of VRK1 with p63 expression and the correlation of VRK2 with ki67 levels are very consistent with the association of VRK1 and VRK2 with a proliferation phenotype as it had been reported in head and neck squamous cells carcinomas." (PMID 24079673, 2013).
Infertility (6 papers, 2010 to 2025). "VRK1-deficient mice of both males and females are infertile, which was considered to be caused by defects in spermatogenesis, oogenesis, or folliculogenesis." (PMID 32266931, 2020). "A VRK1 gene deficiency gives rise to defects in gametogenesis, resulting in infertility in both sexes." (PMID 21179456, 2010). "VRK1 mutant mice generated by the gene trap method showed progressive germ cell loss and resulting infertility." (PMID 21179456, 2010). "In murine models, partial knockdown of VRK1 disrupts gametogenesis, impairing the development of spermatogonia and oocytes and ultimately leading to infertility in both male and female mice." (PMID 39940790, 2025). "This gene has a role in regulating gametogenesis, and disrupted VRK1 function is shown to result in infertile male and female mice." (PMID 21752240, 2011).
liver cancer (6 papers, 2015 to 2025). An epithelial or non-epithelial malignant neoplasm that arises from the liver. "More importantly, VRK1 expression was associated with poor prognosis in liver cancer." (PMID 40234378, 2025). "Intriguingly, VRK1 protein levels were sharply upregulated in liver cancer cell lines Huh7 and HepG2 cells compared with normal hepatocytes THLE-2." (PMID 40234378, 2025). "We next detected VRK1 protein expression levels in normal hepatocytes and several liver cancer cell lines." (PMID 40234378, 2025). "Both VRK1 and VRK3 were shown to promote liver cancer progression, VRK1 regulating G1/S transition and mitosis and VRK3 S phase progression." (PMID 37886173, 2023). "In addition, further studies examined that VRK1 promoted the proliferation and migration of liver cancer cells by upregulating the expression of SNAI1 in vitro." (PMID 40234378, 2025). "The intervention of VRK1 may provide a promising therapeutic strategy for liver cancer." (PMID 40234378, 2025). "VRK1 phosphorylates CHD1L at serine 122 to induce the expression of SNAI1, thereby promoting the proliferation, migration and tumor growth of liver cancer cells." (PMID 40234378, 2025). "Thus, VRK1 may serve as a promising therapeutic target in liver cancer." (PMID 40234378, 2025). "This study further refines the biological functions played by VRK1 in liver cancer progression and explores the mechanism by which the VRK1-CHD1L-SNAI1 axis promotes liver cancer progression." (PMID 40234378, 2025). "This convergence of findings further strengthens the evidence supporting the dysregulation of VRK1 in LIHC and reinforces its potential role as a relevant biomarker in liver cancer." (PMID 38157278, 2023). "In summary, we found that VRK1 interacted with and phosphorylated the CHD1L at S122 site to regulate SNAI1 expression, thus promoting the proliferation, migration and tumor growth of liver cancer cells." (PMID 40234378, 2025).
microcephaly (6 papers, 2017 to 2025). A congenital or acquired developmental disorder in which the circumference of the head is smaller than normal for the person's age and sex. "VRK1 pathogenic variants are associated with pontocerebellar hypoplasia (PCH1A), microcephaly, SMA, ALS, HMN and HMSN." (PMID 40428407, 2025). "From these, the human VRK1 pathogenic alleles are associated with motor and sensory axonal neuropathy and microcephaly." (PMID 35269756, 2022). "Vrk1GT3/GT3 mice had significantly smaller brains (10% lighter, p = 0.00047) than Vrk1+/+ mice, consistent with the microcephaly observed in children with VRK1 mutations." (PMID 30050127, 2018). "To examine if reduced expression of Vrk1 recapitulates the congenital microcephaly observed in children with VRK1 deficiency, we measured brain weight and length of Vrk1+/+ and Vrk1GT3/GT3 male mice." (PMID 30050127, 2018). "It thus remains unknown whether patients with VRK1‐associated motor neuron disease have a predisposition to pontocerebellar hypoplasia or microcephaly, given the few patients with VRK1 mutation that have been described so far and the lack of functional study associated with the reported variants." (PMID 31560180, 2019). "Pathogenic variants of VRK1 have been associated with various neurodevelopmental and neuromuscular disorders, including pontocerebellar hypoplasia (PCH1A), microcephaly, motor and sensorimotor neuropathies and motor neuron disorders." (PMID 40428407, 2025). "Analysis of gene expression data from Vrk1GT3/GT3 mutant cortices highlighted previously known functions of VRK1 in cellular proliferation and the DNA damage response, which are both relevant to microcephaly." (PMID 30050127, 2018). "Development of pontocerebellar hypoplasia or microcephaly in motor neuron disease patients associated with VRK1 has not been a frequent finding in reported cases, with seven patients so far, and it is not a clinical feature in the family reported here." (PMID 31560180, 2019). "The proliferation-related gene sets enriched in the Vrk1GT3/GT3 cortex may be directly related to the smaller brains of the Vrk1GT3/GT3 mice and to the microcephaly phenotype observed in VRK1 homozygous affected humans." (PMID 30050127, 2018). "VRK1 variants have been segregated with motor neuron diseases including SMA phenotypes or hereditary complex motor and sensory axonal neuropathy (HMSN), with or without pontocerebellar hypoplasia or microcephaly." (PMID 31560180, 2019).
motor neuron disease (6 papers, 2018 to 2025). "Rare homozygous or compound heterozygous human VRK1 variants were associated with distal hereditary neuropathies and motor neuron diseases." (PMID 38753965, 2024). "A subgroup of related and heterogeneous motor neuron diseases is associated with rare homozygous or compound heterozygous VRK1 variants." (PMID 38554151, 2024). "Clinical course of VRK1-associated motor neuron disease may reveal very slow rate of progression with extended survival, even with childhood onset." (PMID 40428407, 2025). "The first detailed description of anterior horn cell disease with pontocerebellar hypoplasia in infants was provided by Goutieres in 1977, and since then recessive variants in five genes have been identified as causes of PCH1, including VRK1, EXOSC3, EXOSC8, EXOSC9 and SLC25A46." (PMID 40428407, 2025). "Reported cases of VRK1-related motor neuron disease without associated features have a phenotype similar to the patient reported here." (PMID 36980188, 2023). "Our work provides a basis for future studies of the neuronal functions of VRK1, which may impact other, more common forms of motor neuron disease." (PMID 30050127, 2018). "Because the L200P variant impairs histone H4K16ac induced by DNA damage, we tested whether other known VRK1 variants associated with several motor neuron diseases, and not characterized in this context, have a similar effect." (PMID 38554151, 2024). "Mutations in VRK1, the kinase that phosphorylates BAF during mitosis, are associated with motor neuron disease with or without associated features such as pontocerebellar hypoplasia or intellectual disability." (PMID 36980188, 2023). "Motor neuron disorders and motor neuropathies without neurodevelopmental abnormalities have been reported with PCH1A (VRK1 gene)." (PMID 40428407, 2025).
lung adenocarcinoma (5 papers, 2015 to 2024). A carcinoma that arises from the lung and is characterized by the presence of malignant glandular epithelial cells. "Vaccinia-related kinase 1 (VRK1) is a master regulator in lung adenocarcinoma and is considered a key molecule in the adaptive pathway, which mainly controls cell survival." (PMID 26412148, 2015). "In a gene expression analysis of ninety-two human lung adenocarcinomas, which were compared to its matched controls, high VRK1 expression levels were detected in mitotic networks of lung adenocarcinomas, and its inhibition cooperated with PARP inhibitors to reduce tumor growth." (PMID 31101118, 2019). "The effect of VRK1 depletion, using two different siRNA on epigenetic modifications of histone H3K9 was determined in two different cell lines, A549 lung adenocarcinoma and U2OS osteosarcoma, under two conditions, in the presence and absence of serum." (PMID 37179361, 2023). "The effect of VRK1 depletion and VRK1 inhibitor, VRK-IN-1, on the acetylation and methylation of histone H3 in K4, K9 and K27 was determined under different conditions, arrested or proliferating cells, in A549 lung adenocarcinoma and U2OS osteosarcoma cells." (PMID 37179361, 2023). "Moreover, VRK1 elimination by CRISPR/Cas9 identifies wild-type VRK1 as an overexpressed oncogenic driver gene, consistent with its role in lung adenocarcinomas." (PMID 29679095, 2018).